CDX2 (caudal type homeobox 2)
Diseases named in the same sentence as CDX2 in open-access papers (continued):
Sharing a sentence is not in itself a finding about the gene and the disease.
tumor (continued). "When applying these markers in the diagnostics of tumors of uncertain origin, it needs to be noted that loss of CDX2 and SATB2 expression was associated with higher tumor grade, proximal tumor location, BRAF mutation, and dMMR, which also corresponds with the findings of the previous studies." (PMID 39998677, 2025). "HOXA10 expression also occurred more frequently in GC tissues that expressed caudal type homeobox 2 (CDX2), in which this gene plays an important role in the regulation of intestinal epithelial cells and has been recognized as a possible GC tumor suppressor gene." (PMID 39858044, 2025). "Immunohistochemically, the tumor showed expression of CDX2, CK20 and SAT-B2." (PMID 40758205, 2025). "Analysis of CDX2 expression across the cohort of primary and metastatic tumours demonstrated a range of nuclear expression levels, with significantly higher expression in well/moderately differentiated (low grade) compared to poorly differentiated (high grade) tumours." (PMID 41105300, 2025). "Moreover, consistent with a role for ATRX, HNF4A and CDX2 in maintaining lineage fidelity and suppressing squamous-like plasticity, we observed low expression of these proteins in tumours containing LY6D+ cells." (PMID 40468074, 2025). "For example, knocking down FOXM1 or STAT3 in proximal models may reduce tumor growth, while overexpressing CDX2 or GATA6 could induce a more differentiated, less aggressive phenotype, advancing therapeutic understanding and precision medicine." (PMID 40862793, 2025). "In addition to its homeotic function during gut development, CDX2 is also known to play a tumor suppressor role in cancer progression in the distal colon." (PMID 39036214, 2024). "Additionally, they align with studies highlighting the tumor-suppressive role of the CDX2 gene, which substantially impacts tumor differentiation, correlating moderate or negative CDX2 expression with tumors exhibiting moderate to poor differentiation." (PMID 38786321, 2024). "However, while CDX2’s involvement in tumor progression is well-established, its precise implication in lymph node metastasis remains a subject of active investigation." (PMID 39328205, 2024). "Therefore, further research and assessment of CDX2 levels in tumour tissues is crucial for identifying potential markers that can select patients with worse outcomes and guide treatment decisions to improve survival." (PMID 39201360, 2024). "Additionally, BLM tumor tissue sections exhibited a higher level of CDX2 protein compared to Min tumor tissue." (PMID 38893159, 2024). "Median OS and PFS were significantly inferior for patients with CDX2-negative versus CDX2-positive tumours, even after excluding tumours with the BRAF p.V600E allele." (PMID 38439814, 2024). "CDX2’s influence on Wnt signaling components could substantially shape tumor behavior, potentially impacting metastatic dissemination, including lymph node involvement." (PMID 39328205, 2024). "Conversely, studies suggest that the diminishment of CDX2 expression could correlate with tumor dedifferentiation and heightened aggressiveness, potentially elevating the risk of lymph node metastasis." (PMID 39328205, 2024). "We further analysed the correlation between CXCL12, CD44v6, HIF1A, TGFBR2 and KRT7 expression in metastatic tumor tissues & exosomes with sex, age, habit, Tumor Differentiation grade, TNM stage, EGFR mutation status, AE1, Chromogranin, CDX2, CEA, CK20, TTF-1 & CK7." (PMID 38877052, 2024). "Multiple Cox regression analysis performed to adjust for prognostic covariates (BRAF genotype and tumour sidedness) disclosed a significant decrease in OS for patients with the p.V600E variant (p = 0.029) but not with loss of CDX2 expression." (PMID 38439814, 2024). "Low CDX2 expression is associated with aggressive features such as lack of tumour differentiation and presence of lymphovascular invasion, and it has an increased frequency in advanced-stage and right-sided tumours." (PMID 39201360, 2024).
tumor (continued). "Furthermore, by IHC, BLM tumor tissue had higher levels of CDX2 protein than Min tumors, whereas normal Min and BLM colon tissue had similar levels of CDX2 protein." (PMID 38893159, 2024). "Evaluation of CDX-2 expression in tumor cells was used to verify intestinal origin." (PMID 39036209, 2024). "Similarly, there was a higher number of tumours with low CDX2 expression in the colon (9.2%) than in the rectum (5.7%); however, this relationship with CDX2 was not statistically significant." (PMID 39201360, 2024). "Although this study was not powered to demonstrate predictive value due to small numbers, it was indicative of a trend that tumours with low CDX2 expression may select stage II patients who are more likely to benefit from adjuvant chemotherapy." (PMID 39201360, 2024). "Utilizing the Chi-squared test, we also analyzed the correlation between the subcategories derived from Category 3 of CDX2 nuclear expression and the categories of tumor differentiation patterns, uncovering a statistically significant correlation (p-value = 0.0018)." (PMID 38786321, 2024). "All tumours that lacked CDX2 expression or had the BRAF p.V600E variant were positive for COX2 expression." (PMID 38439814, 2024). "Some studies observed that KRAS mutations more frequently in tumours with CDX2 expression, while other studies did not." (PMID 38439814, 2024). "Furthermore, serial sections were excised from the same tumor blocks for prospective CDX2 and mucin analyses in this study." (PMID 37602699, 2023). "As usual in CMTC, the morular component of this tumor was positive for CDX2." (PMID 36689061, 2023). "Additionally, the positive expression of nuclear YAP and CDX2 proteins was robustly induced in tumor tissues of CSCs-EVs-treated mice while an opposite effect was identified in the presence of sh-H19." (PMID 37005676, 2023). "A mass of evidences considers an important role for CDX2 as a tumor suppressor in CRC." (PMID 36277982, 2022). "Several studies have shown that an absence of CDX2 expression level is negatively associated with tumor grade, excellent differentiation, and a favorable patient prognosis." (PMID 36277982, 2022). "The tumor showed localized expression of synaptophysin and CDX2." (PMID 35027045, 2022). "Moreover, tumor organoids were stained for CDX2 and Ki67 markers with immunohistochemistry (IHC) to investigate gastrointestinal origin and proliferation." (PMID 35721501, 2022). "On further assessment of the correlations among CDX2 and clinical pathological parameters, we suggested that CDX2 was meaningfully related to tumor size (<3 cm and ≥3; P < 0.05), depth grading of tumor invasion (T1+T2 and T3+T4; P < 0.05), and lymph node status (N0 and N1 + N2; P < 0.01)." (PMID 36277982, 2022). "Another study has found that microRNA let-7b is a tumor suppressor, and the binding of CDX2 to let-7b can promote the transcription of let-7b and inhibit the expression of COL11A1, thereby reducing the proliferation, invasion, and migration of breast cancer cells." (PMID 35847935, 2022). "Also, another report described thymic SRCC with different IHC results reporting that the signet ring cell-like tumor cells were positive for CDX2 and CK20. postmortem pathology confirmed an accurate diagnosis of thymic SRCC." (PMID 36482538, 2022). "Several lines of evidences support that CDX2 is a tumor suppressor in CRC." (PMID 35449124, 2022). "The tumor organoid and the patient tumor were significantly positive for the Ki67 and CDX2 markers." (PMID 35721501, 2022). "CDX2 promotes metastatic CRC tumor colonization through mesenchymal-epithelial transition." (PMID 33755595, 2021).
tumor (continued). "The observed increases in mRNA transcripts of the mesenchymal markers vimentin and β -catenin, decreased transcripts of the cell adhesion markers E-cadherin and P-cadherin and loss of differentiation markers CDX2, CK6, CK7 and CK13 are hallmarks of transition to a mesenchymal phenotype tumour cells." (PMID 33906633, 2021). "Although Cdx2 has known roles in intestinal homeostasis and exhibits tumor suppressive functions in some contexts, the mechanism by which it impacts these processes is largely unknown." (PMID 33525395, 2021). "The presence of CDX2-low/absent tumours in general was also significantly associated with the presence of certain histopathological CRC subtypes from both ends of the spectrum of biological aggressiveness (P < 0.001)." (PMID 34616012, 2021). "As a result, CDX2 expression was maintained in areas of tumor differentiation (arrowheads)." (PMID 33755595, 2021). "Conversely, Cdx2 overexpression has been shown to decrease mobility and tumor cell growth in vivo." (PMID 33525395, 2021). "A strong nuclear staining for CDX2 was confirmed in all tumor samples." (PMID 34563241, 2021). "Finally, loss of Cdx2 increased the indices of stem cell character and promoted anchorage independent growth, again consistent with a tumor suppressive role for Cdx2 in CRC." (PMID 33525395, 2021). "Moreover, emerging evidence has demonstrated that CDX2 has tumour‐suppressing properties in CC by attenuating CC cell proliferation, migration invasion and metastasis." (PMID 33621425, 2021). "Most CRCs showed a diffuse CDX2 expression (median: 100% positive tumour cells, mean: 91% positive tumour cells) resulting in 783 CRCs (78%) showing a diffuse nuclear expression in all tumours cells and a total of 85% (852/1003) showing a diffuse nuclear staining in ≥90% of tumour cells." (PMID 34616012, 2021). "Intriguingly, histopathological examination revealed that CDX2 knockdown in the context of LIN28B overexpression dramatically converted the tumor’s differentiation status from well or moderately differentiated, which have gland-like structures, to poorly differentiated." (PMID 33755595, 2021). "Therefore, we next focused on how CDX2 can modulate the CRC tumor progression in the context of LIN28B overexpression." (PMID 33755595, 2021). "However, the majority of cases with either increased tumour budding activity or high WHO grade fell into the CDX2-high category." (PMID 34616012, 2021). "Accordingly, increased MEX3A levels could contribute to the repression of the bona fide tumor-suppressive CDX2 in the intestine." (PMID 34067172, 2021). "CDX2 is a useful immunohistochemical marker of intestinal epithelium and the presence of CDX2 in a tumour of an unknown origin increases the likelihood of a gastrointestinal origin." (PMID 34940086, 2021). "Moreover, CD20 expression was significantly correlated with tumor location (P=0.007), tumor differentiation (P=0.005), and CDX2 expression (P=0.014) in PDAC patients." (PMID 34367978, 2021). "Cdx2 has both tumor promoter and tumor suppressive potential." (PMID 33525395, 2021). "Furthermore, a previous report concluded that SOX9 also inhibited CDX2 protein expression both in intestinal adenocarcinoma cells in vitro and in a nude mouse xenograft tumor model." (PMID 33639844, 2021). "This indicates that CDX2 plays a pivotal role for CRC tumor differentiation." (PMID 33755595, 2021). "Immunohistochemical (IHC) staining was performed using thyroid transcription factor-1 (TTF-1), paired box protein 8 (PAX8), cytokeratin 20 (CK20), caudal-related homeobox transcription factor-2 (CDX-2) and villi protein (Villin) in order to clarify the origin of the tumor." (PMID 32375670, 2020). "In this tumor, negative modulation of the CDX2/miR-615-5p/IGF2 axis was associated with increased tumor size and weight in animal models, as well as increased expression of tumor progression markers such as Ki-67, cyclin D1, c-MYC and Bcl-2." (PMID 32605009, 2020).
tumor (continued). "In our study, we demonstrate that CDX2 loss is an independent negative prognostic tumor marker, even after correcting for these known prognostic factors." (PMID 32117703, 2020). "In fact, RCC2 was found to be an independent prognostic biomarker in multivariable analysis of chemotherapy-untreated stage I–III patients, after adjusting for TNM stage, patient age, sex, tumour location, MSI status, CDX2 expression, BRAFV600E- and KRAS mutation status." (PMID 33219056, 2020). "CDX2-negative tumours are often associated with several adverse prognostic variables (e.g., advanced stage, poor differentiation, vascular invasion, BRAF mutation and CIMP-positive status) and lower DFS." (PMID 33209121, 2020). "For patients with CDX2 status available, 21% had a BRAF V600E mutation (BRAFmut), 41% a KRAS mutation (KRASmut), 8% were MSI high (MSI-H), and 38% double (KRAS and BRAF) wild-type tumor." (PMID 32117703, 2020). "In a cohort of CRC patients, expression levels of CDX2 are inversely correlated with tumor grading." (PMID 31591478, 2020). "To confirm whether intestinal identity of epithelial tissue is maintained under culture conditions, we compared the expression of CDX2 in primary tumour and PDCOs." (PMID 31906589, 2020). "Our result showed a significant increase in CDX2 expression in tumour explants treated with AM404." (PMID 31906201, 2019). "Therefore, to associate AM404 with cellular differentiation and stem-like activity, we utilized CDX2 and CD44v6 as markers for differentiation and ‘stemness’ in tumour explants." (PMID 31906201, 2019). "This CDX2-negative group consisted of two staining patterns; a score of 0 (a complete loss of CDX2 expression) was observed in 1.7% of patients (n = 3/174), and a score of 0.5 (scattered and faint CDX2 expression in a minority of tumor cells) was found in 4.6% of patients (n = 8/174)." (PMID 31783700, 2019). "The results showed the xenograft tumor tissues formed by CDX2-knockdown cells demonstrated a much stronger Ki67-staining score than those formed by the control cells, whereas the xenograft tumor tissues formed by CDX2-overexpressing cells had the opposite effect." (PMID 30631044, 2019). "The tumor cells demonstrated loss of E-cadherin, with negative CDX-2, p63, NKX3.1, PAX-2, and PSA expression." (PMID 31638990, 2019). "The CDX2-positive group showed two staining patterns: a score of 2 (moderate/strong staining in most tumor cells) was observed in 37.9% of patients (n = 66/174), and a score of 3 (strong staining in all tumor cells) was observed in 55.7% of patients (n = 97/174)." (PMID 31783700, 2019). "Some 235 of 238 consecutive dMMR tumours were assessed for CDX2 status." (PMID 30511046, 2018). "The poor prognostic impact of the reduced expression of CDX2 on the OS remained significant in multivariate analyses that included sex, tumor grade, and synchronous or metachronous liver metastasis as the confounding variables (HR 2.41; 95% CI, 1.52–3.85; P < 0.001)." (PMID 30326864, 2018). "The CDX2 expression was evaluated by immunohistochemistry on whole tumour sections." (PMID 30425348, 2018). "The percentage of CDX2 immunostained tumor cells was 66% on average, with a median of 78.8%." (PMID 30257705, 2018). "CDX2 is a caudal-homeobox gene and its expression is abnormal in numerous tumour cell types." (PMID 29179508, 2017). "Moreover, various clinical studies suggest that CDX2 expression is often lost in cancers with high tumour grade and advanced tumour stage." (PMID 29179508, 2017). "These tumours can aberrantly express CDX2 and form a glandular pattern." (PMID 28494767, 2017). "Decreased expression of CDX2 is often observed at the invasive front and in tumor buddings." (PMID 26910375, 2016).
tumor (continued). "Notably, loss of the intestinal factor CDX2 in CRC has been associated with progression, increased tumour grade and high mortality." (PMID 27586588, 2016). "Additionally, it has been demonstrated that CDX2 functions as a tumor suppressor in the adult colon." (PMID 26005051, 2015). "Primary pulmonary enteric adenocarcinoma (PEAC) is defined as a pulmonary adenocarcinoma with a predominant component (>50 %) of intestinal differentiation and with tumor cells positive for at least one intestinal marker such as caudal-related homeobox 2 (CDX2), CK20, or MUC2." (PMID 26677401, 2015). "CDX2 tumor suppression may also function via the extracellular signal-regulated kinase 1/2 pathway in CRC." (PMID 25847407, 2015). "Furthermore, the overexpression of CDX2 upregulated the expression of Bax and downregulated the expression levels of survivin, Bcl-2, cyclin D1, Skp2 and c-Myc in the tumor tissues." (PMID 25738600, 2015). "Recent evidence also suggests that Cdx2 may play a substantial role in Wnt signaling as a tumor suppressor gene and therefore inhibit EMT." (PMID 25806371, 2015). "In this regard, CDX2 might function as a tumor suppressor in pancreas to suppress the development and/or progression of PanIN." (PMID 24489794, 2014). "As PanIN has widely been accepted as noninvasive precursor lesions of PDAC, our data suggest that CDX2 might function as a tumor suppressor in pancreas." (PMID 24489794, 2014). "However, strong uniform expression of CDX2 was noted in certain types of tumor outside of GI tract such as mucinous ovarian carcinomas and adenocarcinomas primary to the urinary bladder." (PMID 24489794, 2014). "Furthermore, the activation of EphA2 receptor with ephrinA1 induced cdx-2, a tumor suppressor gene in A549 cells." (PMID 22824143, 2012). "Previous studies showed that CDX2 is expressed in normal and neoplastic intestinal epithelial cells with a relatively high sensitivity and specificity and that it can be used as an immunohistochemical marker for neoplasms of intestinal origin." (PMID 22268990, 2012). "Activation of NSCLC cells with ephrin-A1 leads to tumor growth inhibition via cdx-2 expression." (PMID 22824143, 2012). "It is likely that other methods of assessing absolute levels of CDX2 expression might show differences related to tumor differentiation." (PMID 22268990, 2012). "We conclude that receptor EphA2 activation by ephrin-A1 induces tumor suppressor gene cdx-2 expression which attenuates cell proliferation, tumor growth and thus may be a promising therapeutic target against NSCLC." (PMID 22824143, 2012). "They concluded that CDX2 expression decreases with tumor differentiation." (PMID 22268990, 2012). "Furthermore, silencing cdx-2 gene expression before ephrin-A1 treatment increased claudin-2 expression along with increased cell proliferation and tumor growth in A549 cells." (PMID 22824143, 2012). "In the present study we hypothesized that EphA2 signaling modulates claudin-2 gene expression via induction of cdx-2, a tumor suppressor gene in NSCLC cells." (PMID 22824143, 2012). "The suppressive function of CDX2 on tumor cell proliferation observed in several studies has been explained by CDX2-mediated activation of negative cell cycle regulators, such as cyclin-dependent kinase inhibitor 1A (CDKN1A), a known inhibitor of G1 cyclin/cyclin-dependent kinase complexes." (PMID 19781065, 2009). "Cdx2 appears to play critical roles in gut differentiation, proliferation and neoplasia, and it was recently demonstrated that the gastric mucosa of transgenic Cdx2-overexpressing mice are morphologically changed to intestinal metaplastic mucosa including microvilli and PepT1 expression." (PMID 18575574, 2008).